FBXO47 (F-box protein 47)
Description:
Probably recognizes and binds to some phosphorylated proteins and promotes their ubiquitination and degradation.
Tractability: No criterion of Open Targets' tractability assessment is met for any kind of drug.
Gene: Protein-coding gene on chromosome 17 (38,936,432 to 38,967,403, reverse strand). Ensembl gene ENSG00000204952.
Gene Ontology:
Biological process: SCF-dependent proteasomal ubiquitin-dependent protein catabolic process
Cellular component: SCF ubiquitin ligase complex
Genetic constraint (gnomAD): Loss-of-function variants: 18 observed, 32.81 expected, observed/expected ratio (o/e) 0.55, 90% interval 0.38 to 0.81. The upper end of that interval is the gene's LOEUF score, 0.81, which puts it in group 3 of 6, group 1 being the genes least tolerant of losing a copy. Missense variants: 353 observed, 393.89 expected, observed/expected ratio (o/e) 0.9, 90% interval 0.82 to 0.98. Synonymous variants: 115 observed, 130.12 expected, observed/expected ratio (o/e) 0.88, 90% interval 0.76 to 1.03.
Homologues: Orthologues: chimpanzee FBXO47 (99% identical), macaque FBXO47 (91% identical), dog FBXO47 (91% identical), pig FBXO47 (88% identical), rabbit FBXO47 (87% identical), mouse Fbxo47 (83% identical), rat Fbxo47 (81% identical), guinea pig FBXO47 (73% identical), tropical clawed frog fbxo47 (58% identical).
Diseases named in the same sentence as FBXO47 in open-access papers:
FBXO47 is named in the same sentence as 9 diseases in open-access papers, as found by Europe PMC text mining. Sharing a sentence is not in itself a finding about the gene and the disease. The quoted sentences say what the papers report.
gastric cancer (4 papers, 2020 to 2022). A primary or metastatic malignant neoplasm involving the stomach. "The tRF-3019a was reported to modulate gastric cancer cell proliferation, migration and invasion by targeting FBXO47, and it may serve as a potential diagnostic biomarker for gastric cancer." (PMID 36230476, 2022). "For instance, recently, a 3-tsRNA has been stated to enhance cell proliferation, migration, and invasion in gastric cancer by targeting FBXO47." (PMID 35456407, 2022). "For example, TRF-3019a inhibits gastric cancer cell proliferation by directly regulating the tumour suppressor gene FBXO47." (PMID 34341710, 2021). "Studies have shown that TRF-3019a regulates gastric cancer cells by directly regulating the tumour suppressor gene FBXO47." (PMID 34341710, 2021). "Furthermore, tRF-3019a (3′-tRF of tRNAAlaAGC) upregulation was reported to facilitate cell proliferation and invasion in gastric cancer by targeting FBXO47, while 5′-tRF-LeuCAG promoted both cell proliferation and cell cycle progression in non-small cell lung cancer through AURKA downregulation." (PMID 33291319, 2020).
male infertility (2 papers, 2020 to 2021). The inability of the male to effect fertilization of an ovum after a specified period of unprotected intercourse. "By contrast, Dydc1 has been reported to regulate acrosome biogenesis during mice spermatogenesis and Fbxo47 was shown to be specifically expressed in meiotic prophase I and gene knockout leads to male infertility in mice." (PMID 34499650, 2021).
tumor (6 papers, 2022 to 2025). "TSHZ2 and FBXO47 have been implicated in the regulation of the cell cycle by controlling key molecules involved in this process, and their alteration could contribute to tumor progression." (PMID 40136626, 2025). "However, genes involved in antioxidant defense (GSTO1), apoptosis process (DUSP8), and tumor suppressor (KIAA1324, FBXO47, NME6) were upregulated in mycotoxins-exposed animals, suggesting activation of the antioxidant defense in response to mycotoxicity." (PMID 37744913, 2023).
FBXO47 also shares sentences with these, for which no sentence is quoted: cancer (4 papers); infertile (1); neurodegenerative disease (1); non-small cell lung carcinoma (1); papillary renal cell carcinoma (1); renal carcinoma (1).